SELENOP (selenoprotein P)
Diseases named in the same sentence as SELENOP in open-access papers (continued):
Sharing a sentence is not in itself a finding about the gene and the disease.
type 2 diabetes (continued). "Serum levels of selenoprotein P are elevated during aging and in people with type 2 diabetes, non-alcoholic fatty liver disease, and hepatitis C. However, how serum levels of full-length selenoprotein P are regulated largely remains unknown, especially in the general population." (PMID 33693023, 2021). "Moreover, circulating selenoprotein P levels are negatively correlated with adiponectin levels in type 2 diabetes patients, in agreement with observations from selenoprotein P-deficient mice, suggesting its involvement in signaling crosstalk with other organokines." (PMID 34944728, 2021). "Thus if an increase in selenoprotein P concentration is the cause of increased type-2 diabetes risk as suggested by some authors, no adverse effect of additional Se would have been seen, as was indeed the case." (PMID 23028897, 2012). "Although Misu and colleagues found a correlation between selenoprotein P and circulating adiponectin in 36 type-2 diabetics, it was not strong, explaining only 13% of the variance in adiponectin concentration." (PMID 23028897, 2012).
breast carcinoma (20 papers, 2013 to 2026). "Accordingly, low serum Se and SELENOP concentrations as well as low serum GPx3 activity have been associated with higher risk of mortality and recurrence after breast cancer diagnosis." (PMID 37741974, 2023). "Low concentrations of serum selenium (Se) and its main transporter selenoprotein P (SELENOP) are associated with a poor prognosis following breast cancer diagnosis." (PMID 35636018, 2022). "Nowadays, more and more studies have demonstrated that several polymorphisms of the selenoprotein P gene (SEPP1) were associated with susceptibility of tumors, including breast cancer (BC), colorectal cancer (CRC), and PCa." (PMID 34616844, 2021). "Studies showed that genetic variants in SELENOP were associated with the risk of breast cancer, prostate cancer, advanced colorectal adenoma and colorectal cancer as well as first phase insulin response and the occurrence of abdominal aortic aneurysm." (PMID 28499373, 2017). "SEPP1 (selenoprotein P, plasma, 1) has been associated with breast cancer risk among women with higher Native American ancestry." (PMID 25857299, 2015). "Patients were also analyzed for SELENOP-aAb, to identify whether tumorigenesis associates with a higher prevalence of autoimmunity to SELENOP, as observed before in breast cancer." (PMID 40435558, 2025). "Biosynthesis of potentially modified SELENOP by malignant cells may cause the development of SELENOP-aAb, and patients with breast cancer may consequently tend to develop autoimmunity to Se transport." (PMID 35636018, 2022). "In how far a predisposition to breast cancer is exerted by SELENOP-aAb, or whether modified SELENOP is secreted from malignant breast tissue is unknown at present." (PMID 35636018, 2022). "SELENOP and PKMYT1 are novel immunomodulatory factors related to multiple pathological indicators of breast cancer and can be used as diagnostic biomarkers." (PMID 40821907, 2025). "We collected breast cancer tissue samples from 60 volunteers and performed IHC experiments to validate the expression of SELENOP, PKMYT1 and immune checkpoints in BRCA tissue." (PMID 40821907, 2025). "This study establishes SELENOP and PKMYT1 as key metabolic-immune regulators reprogramming the breast cancer microenvironment, serving as diagnostic biomarkers and therapeutic targets." (PMID 40821907, 2025). "Polymorphisms in selenoprotein genes, such as GPx1 and selenoprotein P (SELENOP), can influence how selenium impacts breast cancer." (PMID 40901095, 2025). "Increased expression of LRP8, a low-density lipoprotein receptor that also functions as a receptor for selenoprotein P (SELENOP), was identified to promote ferroptosis resistance in breast cancer and hepatocellular carcinoma cell lines." (PMID 36358931, 2022). "Even though we have controlled for the most important potential confounders of breast cancer recurrence, information on other autoimmune diseases, prior inflammatory events or other potential triggers for autoimmunity against SELENOP are missing." (PMID 35636018, 2022). "The higher prevalence of SELENOP-aAb in breast cancer patients as compared to healthy subjects or Hashimoto patients implies a potential role of SELENOP-aAb in risk for developing breast cancer." (PMID 35636018, 2022). "In this study, we explore the expression levels of SELENOF and eIF4a3, along with genotypes of SELENOF and the selenium transporter SELENOP, in breast cancer tissues from African American and Caucasian women using a tissue microarray (TMA) with relevant clinical data." (PMID 41563517, 2026). "Previously in the cohort used in this study, serum Se, serum SELENOP concentrations, activity of the serum GPx3 as well as novel autoantibodies targeting SELENOP were shown to be independent predictors of survival after breast cancer diagnosis, outperforming established clinical prognostic markers." (PMID 37741974, 2023).
breast carcinoma (continued). "Moreover, we speculated that a combination of three markers of Se status, namely total-Se, activity of the extracellular selenoprotein glutathione peroxidase-3 (GPx3) and concentration of SELENOP provides more accurate prognostic information than a single marker alone in breast cancer." (PMID 40435558, 2025). "SELENOP-aAb along with serum Se, SELENOP and GPX3 activity were determined in serum samples of 1988 patients with a new diagnosis of breast cancer enrolled in the multicentre SCAN-B study." (PMID 35636018, 2022). "Secondly, the mechanisms of SELENOP and PKMYT1 in the occurrence and development of breast cancer remain unclear, which will be the focus of subsequent experimental research." (PMID 40821907, 2025). "Overall, considering both the CCLE and LINCS datasets, eight selenoproteins were overexpressed (DIO2, GPX1, GPX4, SELENOI, SELENON, SELENOS, TXNRD1 and TXNRD3) and five were down-expressed (DIO1, GPX2, GPX3, SELENOP and SELENOW) in TNBC compared to all other “non-TNBC” breast cancer subtypes." (PMID 35158912, 2022).
COVID-19 (20 papers, 2020 to 2025). A disease caused by infection with severe acute respiratory syndrome coronavirus 2. "Because of an inverse correlation between selenium levels and COVID-19 survival rates, they concluded “that selenium status [selenium and selenoprotein P] analysis in COVID patients provides diagnostic information”." (PMID 37241870, 2023). "Serum total Se and selenoprotein P levels were found to be associated with improved outcome in COVID-19 cases." (PMID 33920813, 2021). "Zn deficiency in surviving COVID-19 patients was found in 40.9% of samples, a combined Zn and Se deficit in 22.6% of samples, and a combined Zn and SELENOP deficit in 19.7% of samples." (PMID 33126054, 2021). "In this manuscript, we report that patients suffering from COVID-19 display a deficiency in the essential trace element Se in blood, along with low concentrations of the Se transporter SELENOP and low enzymatic activity of the secreted GPx3." (PMID 32708526, 2020). "Moreover, lower serum Se and SELENOP levels were found to be associated with higher COVID-19 mortality." (PMID 33920813, 2021). "In the samples of deceased COVID-19 patients, 64.7% and 70.6% showed Se and SELENOP deficiency, respectively, whereas 39.3% and 32.6% of the samples from the survivors had to be classified as Se- and SELENOP-deficient, respectively." (PMID 32708526, 2020). "Possible direct evidence for this effect is the observation reported by Schomburg and coworkers that SelenoP concentrations are lower in COVID-19 cases than in uninfected controls, and decrease with increasing disease severity." (PMID 36978807, 2023). "In another cross-sectional study conducted in Belgium, the trace elements (Se, Zn, Fe and Cu, GPX3 activity and selenoprotein P (SELENOP) levels were determined in the serum of COVID-19 patients." (PMID 35563199, 2022). "In view that the Se status biomarker and Se transporter selenoprotein P (SELENOP) is also particularly low in COVID-19, we tested the prevalence of a combined deficit, i.e., serum Zn below 638.7 μg/L and serum SELENOP below 2.56 mg/L." (PMID 33126054, 2021). "Correspondingly, both serum Se and selenoprotein P (SELENOP) levels were found to be lower in COVID-19 patients with low values (<2.5 of the reference population) observed in 43.4% and 39.2% cases, respectively." (PMID 33920813, 2021). "Serum samples (n = 166) from COVID-19 patients (n = 33) were collected consecutively and analyzed for total Se by X-ray fluorescence and selenoprotein P (SELENOP) by a validated ELISA." (PMID 32708526, 2020). "Nonetheless, it is of considerable interest that in COVID-19 patients, there may be a specific knockdown of SelenoP." (PMID 36978807, 2023). "In another cohort of COVID-19, non-survivors were characterized by an overrepresentation of a simultaneous zinc and selenium transporter selenoprotein p (SELENOP) deficiency." (PMID 36986247, 2023). "However, a recent study showed that daily intravenous selenium (1 mg Sel) in a cohort of COVID-19 patients with severe ARDS for a total of two weeks elevated their selenoprotein P and GPX3 levels." (PMID 37888066, 2023). "Of the significantly dysregulated proteins, selected immune-related proteins PZP, SELENOP, PON1, and CBP2 were validated as candidate prognostic biomarkers for COVID-19 symptomatology." (PMID 34566994, 2021). "However, in addition to soil and hair, other studies began to analyse the presence of selenium and its biomarkers such as selenoprotein P (SELENOP) in blood, evaluating its role in COVID-19." (PMID 37528833, 2023). "We conclude that the alterations in serum biomarkers of Cu and Se status in COVID-19 are not compatible with a simple acute phase response, and that serum Cu and SELENOP levels contribute to a good prediction of survival." (PMID 34072977, 2021).
Obesity (19 papers, 2011 to 2025). Accumulation of substantial excess body fat. "Selenoprotein P (SeP) is a hepatokine responsible for the delivery of selenium into various cells and is an obesity-associated browning factor." (PMID 36674862, 2023). "The elevated concentration of selenoprotein P was reported in various CMDs, such as obesity, DM, NAFLD and CVD, all closely related to psoriasis." (PMID 32605214, 2020). "This research highlights the significance of selenium and its carrier proteins in the nutritional evaluation of obese children, suggesting the potential value of selenium status, especially via selenoprotein-P levels, as a biomarker for obesity in the pediatric population." (PMID 39000383, 2024). "Selenoprotein P may be a novel indicator of inflammation and the metabolic complications development in psoriatics, especially with severe form or with concomitant obesity." (PMID 32605214, 2020). "Moreover, circulating SELENOP levels correlated with HOMA-IR and were more than 3-fold higher in patients with obesity (52.3 ± 39.1 vs. 14.5 ± 12.8 μg/mL, p < 0.001), whereas SAT SELENOP mRNA expression was significantly associated with BMI." (PMID 32344656, 2020). "It has also been demonstrated that obesity upregulates the hepatic expressions of MsrB1, SELENON, SELENOP, and SELENOW, as well as GPx4 in diabetic patients by 33–35% compared to non-obese subjects." (PMID 37895024, 2023). "Other studies concluded that SELENOP gene expression in 3T3-L1 adipocytes was reduced in response to TNF-α or H2O2 treatment, indicating a link between adipose tissue inflammation and oxidative stress in obesity and altered selenoprotein metabolism." (PMID 37895024, 2023). "Se status in obesity has been investigated in a number of studies using various biomarkers including more routine ones like Se levels in different tissues, as well as functional biomarkers, such as GPX activity and SELENOP levels." (PMID 32344656, 2020). "For obesity, the ELISA found no significance (SMD = 0.38, 95% CI: −0.02 to 0.77, n = 5), but the SPIA indicated higher SELENOP levels in patients than in the controls (SMD = 22.96, 95% CI: 15.80 to 30.13, n = 1)." (PMID 35883754, 2022).
selenium deficiency (19 papers, 2006 to 2025). A nutritional deficiency disease resulting from inadequate selenium levels in the body, which can lead to impaired function of selenoproteins essential for antioxidant defense and thyroid hormone metabolism. "Kiyohara’s research demonstrated that selenium deficiency/absence, inhibition of GPx4, and loss of antioxidant function in SELENOP KO mice are responsible for the increased Zn2+ levels." (PMID 39941073, 2025). "The knockout of SELENOP increases seizures in selenium deficiency, while brain-specific knockout of all selenoproteins leads to severe seizures." (PMID 37895024, 2023). "SELENOP concentration in the serum or plasma has been shown to be a valuable diagnostic parameter for selenium deficiency." (PMID 35056706, 2022). "Maternal selenium deficiency led to a reduction (Ptrt < 0.05) in SelenoP expression within offspring livers." (PMID 32210049, 2020). "Synthesis of SelenoP has been proven to decrease concomitant to selenium deficiency, causing plasma concentrations to decline, although SelenoP expression has previously been shown to increase prior to pregnancy and reach maximum levels at full-term in mice." (PMID 32210049, 2020). "For full expression of the extracellular selenoprotein P, a concentration of >90–140 μg/L is needed, implying that a selenium deficiency in fact existed before the intervention and during the whole period in the placebo group." (PMID 29641571, 2018). "Other disorders include neurologic phenotypes due to, for instance, the selenium deficiency in the brain caused by impaired selenium transport in the selenoprotein P-deficient mice." (PMID 30205557, 2018). "However, the gene expressions of type I iodothyronine deiodinase and selenoprotein P were more resistant to selenium deficiency-related decline than glutathione reductase." (PMID 30205557, 2018). "Selenoprotein P (Sepp1) and its receptor, apolipoprotein E receptor 2 (apoER2), account for brain retaining selenium better than other tissues, Sepp1-apoER2 interactions supply selenium for maintenance of brain neurons, to protect the severe neurodegeneration and death in mild selenium deficiency." (PMID 26770661, 2016). "Apart from the systemic inflammatory response, selenium deficiency should be understood as a true low selenium status with decreased tissue selenoenzyme activity and that this deficiency leads to low plasma selenium concentration, as well as low selenoprotein P or glutathione peroxidase." (PMID 24886623, 2014). "In the brain, SELENOW is one of the selenoproteins whose expression is most affected by SELENOP, although dietary selenium deficiency does not decrease SELENOW levels, it reduces GPx activity." (PMID 39941073, 2025). "Although selenium deficiency correlates with colorectal cancer (CRC) risk, the roles of the selenium-rich antioxidant selenoprotein P (SELENOP) in CRC remain unclear." (PMID 37166989, 2023). "Selenium and SELENOP levels were positively associated with total and femoral trochanter bone mineral density in subjects without selenium deficiency." (PMID 35056706, 2022). "While selenium treatment elevated serum selenium and SELENOP concentrations but not GPx3 activity in the full patient cohort, subgroup analyses revealed that GPx3 activity increased in patients with reduced kidney function, selenium deficiency and low to moderate GPx3 activity." (PMID 38063975, 2023).
prostate carcinoma (17 papers, 2012 to 2025). A carcinoma that arises from epithelial cells of the prostate gland. "A genetic interaction between SELENOF and SELENOP polymorphisms (rs3877899, rs7579 ) impacting prostate cancer risk was identified in a cohort of European men." (PMID 32806741, 2020). "Such a relationship was observed between the rs1050450 polymorphism of the GPX1 gene (glutathione peroxidase 1) and the following neoplasms: breast, prostate, bladder and lungs and the rs7579 polymorphism of the SEPP1 gene (selenoprotein P1) with colorectal and prostate cancer." (PMID 35205233, 2022). "Knockdown of SELENOP expression in prostate cancer cells resulted in increased production of ROS and attenuated cell viability in vitro." (PMID 37765058, 2023). "For example, GPX1, SELENOF, and SELENOP levels were significantly reduced in prostate cancer models, whereas GPX2 was significantly increased." (PMID 32933107, 2020). "SELENOP variants also interact with polymorphisms in the SOD2 gene, which encodes another antioxidant protein, MnSOD, to affect prostate cancer risk." (PMID 32806741, 2020). "A functional interaction between selenoproteins and prostate cancer has been reported, i.e. serum Se and selenoprotein P (SePP) concentrations are reduced in prostate cancer patients and this is correlated with disease severity." (PMID 23133653, 2012). "Finally, a decreased level of selenoprotein P has been noted in patients with colorectal or prostate cancer and cerebrovascular events." (PMID 32605214, 2020). "Furthermore, SELENOP is reported to be downregulated in 68% of prostate cancer tissues." (PMID 37765058, 2023). "A recent study on SELENOP (SEPP1) has led to the identification of several single nucleotide polymorphisms (SNPs) which decrease the expression or function of this metal in various tumor types, including hepatocellular carcinomas, gastric adenocarcinomas, colorectal cancer, and prostate cancer." (PMID 32426284, 2020).
colorectal cancer (14 papers, 2013 to 2025). A primary or metastatic malignant neoplasm that affects the colon or rectum. "Elevated SELENOP level was inversely correlated with colorectal cancer risk." (PMID 35433131, 2022). "Four Se markers, namely total-Se, the circulating selenoproteins GPx3 and SELENOP, and autoantibodies to SELENOP, were analyzed in participants of the ongoing Colorectal Cancer Study of Austria (CORSA)." (PMID 40435558, 2025). "SELENOP, as the main selenoprotein in plasma, plays an important role in the development of colon cancer, and the down-regulation of SELENOP can promote the occurrence of colorectal cancer." (PMID 35624837, 2022). "We aimed to examine the prospective association between manganese, iron, copper, zinc, iodine, selenium, selenoprotein P, free zinc, and their interplay, with incident type 2 diabetes (T2D), cardiovascular disease (CVD) and colorectal cancer (CRC)." (PMID 33590281, 2021).
hepatocellular carcinoma (14 papers, 2015 to 2025). A malignant tumor that arises from hepatocytes. "The study aims to understand how selenoprotein P levels relate to the severity of hepatocellular carcinoma and its impact on patient outcomes." (PMID 39001444, 2024). "The keywords in the first five clusters indicate that LECT2 research has achieved more significant results in human hepatocellular carcinoma, systemic inflammation, chemotactic factor, selenoprotein p and JNK-dependent inhibition." (PMID 38881894, 2024). "In the case of human hepatoma Li-7 cells, the decrease in SELENOP protein levels in whole-cell lysates was also induced by CCDC152 transfection without the significant change of SELENOP mRNA levels." (PMID 34142161, 2021). "In human hepatoma cell line HepG2 cells, HBx induces lipid peroxidation through suppressing selenoprotein P, thereby increasing TNFα expression." (PMID 34615538, 2021).